OR4N2 (olfactory receptor family 4 subfamily N member 2)
Description:
Odorant receptor.
Synonyms: OR14-13; OR14-8
Tractability: Antibody: UniProt places it where antibodies can reach, with medium confidence; UniProt predicts a signal peptide or a membrane-spanning region; its Gene Ontology location is reachable by antibodies, with medium confidence.
Gene: Protein-coding gene on chromosome 14 (19,719,015 to 19,830,253, forward strand). Ensembl gene ENSG00000176294.
Subcellular location: Cell membrane
Pathways (Reactome):
Sensory Perception: Expression and translocation of olfactory receptors
Gene Ontology:
Molecular function: olfactory receptor activity; G protein-coupled receptor activity
Biological process: detection of chemical stimulus involved in sensory perception of smell; G protein-coupled receptor signaling pathway
Cellular component: plasma membrane; membrane
Genetic constraint (gnomAD): Loss-of-function variants: 0 observed, 0.12 expected, observed/expected ratio (o/e) 0, 90% interval 0 to 1.89. That is too few expected variants to judge how well the gene tolerates losing a copy. Missense variants: 307 observed, 335.5 expected, observed/expected ratio (o/e) 0.92, 90% interval 0.83 to 1.01. Synonymous variants: 141 observed, 123.27 expected, observed/expected ratio (o/e) 1.14, 90% interval 1 to 1.32.
Homologues: Orthologues: macaque OR4N2 (96% identical), dog OR4N2 (91% identical), rabbit OR4N2 (88% identical). Paralogues in human: OR4N4 (86% identical), OR4N4C (86% identical), OR4N5 (84% identical), OR4M1 (55% identical), OR4M2 (54% identical), OR4M2B (54% identical), OR4D5 (52% identical), OR4D1 (50% identical), OR4E2 (50% identical), OR4D2 (50% identical), OR4D11 (50% identical), OR4K14 (50% identical), and 116 more.
Diseases named in the same sentence as OR4N2 in open-access papers:
OR4N2 is named in the same sentence as 4 diseases in open-access papers, as found by Europe PMC text mining. Sharing a sentence is not in itself a finding about the gene and the disease. The quoted sentences say what the papers report.
epithelial ovarian cancers (1 paper, 2022). "OR4N2 was shown to be mutated on at least two sites in epithelial ovarian cancers." (PMID 36134028, 2022).
cancer (2 papers, 2019 to 2024). A tumor composed of atypical neoplastic, often pleomorphic cells that invade other tissues. "The list of 78 also included five encoding membrane proteins, namely SLCO6A1, ZP4, OR2C3, OR1N1, and OR4N2, which are potential pan-cancer targets for CAR-T and antibody-drug conjugates." (PMID 39561714, 2024).
tumor (1 paper, 2024). "The specific expression of OR4N2 in neoplastic cells suggests a possible role in tumor cell survival or proliferation, whereas the up-regulation of OR2B11 in TAMs points to a role in shaping the TME to support tumor growth." (PMID 39769144, 2024). "DEG analysis revealed that OR4N2 was up-regulated in neoplastic cells as well as GBM tissues, suggesting its potential tumor-intrinsic function." (PMID 39769144, 2024).
OR4N2 also shares sentences with these, for which no sentence is quoted: bipolar disorder (1 paper).